SNORA15 (small nucleolar RNA, H/ACA box 15)
Synonyms: ACA15; SNORA15A
Gene: Small nucleolar RNA gene on chromosome 7 (56,060,470 to 56,060,602, forward strand). Ensembl gene ENSG00000207168.
Gene Ontology:
Biological process: RNA processing
Cellular component: nucleolus
Homologues: Orthologues: macaque SNORA15 (96% identical), mouse Snora15 (81% identical), rat LOC120096108 (80% identical). Paralogues in human: SNORA15B-1 (98% identical), SNORA15B-2 (98% identical).
Diseases named in the same sentence as SNORA15 in open-access papers:
SNORA15 is named in the same sentence as 4 diseases in open-access papers, as found by Europe PMC text mining. Sharing a sentence is not in itself a finding about the gene and the disease. The quoted sentences say what the papers report.
dyskeratosis congenita (1 paper, 2021). Dyskeratosis congenita (DC) is a rare ectodermal dysplasia that often presents with the classic triad of nail dysplasia, skin pigmentary changes, and oral leukoplakia associated with a high risk of bone marrow failure (BMF) and cancer. "Down-regulation of box H/ACA snoRNAs (such as SNORA15 and SNORA24) has been associated with human diseases including dyskeratosis congenita and leukemia." (PMID 33561224, 2021).
SNORA15 also shares sentences with these, for which no sentence is quoted: leukemia (1 paper); malignant tumors (1); melanoma (1).